DBH (dopamine beta-hydroxylase)
Diseases named in the same sentence as DBH in open-access papers (continued):
Sharing a sentence is not in itself a finding about the gene and the disease.
attention deficit-hyperactivity disorder (2 papers, 2013 to 2018). A disorder characterized by a marked pattern of inattention and/or hyperactivity-impulsivity that is inconsistent with developmental level and clearly interferes with functioning in at least two settings (e.g. at home and at school). "The present study was aimed to investigate the relationship between polymorphism of serotonin receptor 1B gene (HTR1B) and Dopamine beta-hydroxylase gene (DBH) with attention-deficit hyperactivity disorder in adults with or without substance use disorders." (PMID 30246098, 2018). "The findings indicated that genotype and allele frequency difference of HTR1B (rs130058) and DBH (rs2519152) genes are not different in the attention-deficit hyperactivity disorder group, substance use disorder group, the group with patients suffering from both disorders, and control group." (PMID 30246098, 2018). "In case of DBH gene-Rs2519152, the findings indicated that TT, TC, and CC genotypes and T and C alleles are not different in the attention-deficit hyperactivity disorder group, substance use disorder group, the group with patients suffering from both disorders, and control group." (PMID 30246098, 2018). "•The relationship between attention-deficit hyperactivity disorder and HTR1B and DBH genes has not studied before." (PMID 30246098, 2018).
Cognitive impairment (2 papers, 2020 to 2025). Abnormal cognition is characterized by deficits in thinking, reasoning, or remembering. "DBH rs1611115 was associated with an increased risk for impaired cognition in PD." (PMID 33013295, 2020).
COVID-19 (2 papers, 2022 to 2025). A disease caused by infection with severe acute respiratory syndrome coronavirus 2. "Our results showed that SARS-CoV-2 infection did not affect the expression of DBH and VMAT2, but elevated, however, the mRNA levels of MAOA and MAOB in infected cells and in the whole blood samples of hospitalized COVID-19 patients." (PMID 36611805, 2022).
deafness (2 papers, 2015 to 2023). An inherited or acquired condition characterized by the complete loss of the ability to hear from one or both ears. "Depending upon the IC subdivision examined, deafness related decreases in TH production (not dopamine beta hydroxylase (DBH) or phenylethanolamine-N-methyl transferase (PNMT)) can be either transient (days to weeks) or long lasting, i.e., months." (PMID 26257610, 2015).
dyslexia (2 papers, 2018 to 2023). A learning disorder characterized by an impairment in processing written words. "KIAA0319, FOXP2, and DCDC2-KIAA0319 SNPs correlated with dyslexia; DCDC2-DYX1C1 SNPs associated with ADHD; COMT1, MAOA, DBH SNPs correlated with different dysfunctions." (PMID 36970271, 2023). "We examined 4 SNPs located on genes previously associated to dyslexia (KIAA0319, DCDC2, DYX1C1 and FOXP2) and 3 SNPs within genes related to ADHD (COMT, MAOA and DBH) in a cohort of Spanish children (N = 2078) that met the criteria of having one, both or none of these disorders (dyslexia and ADHD)." (PMID 30379906, 2018).
hypoglycaemia (2 papers, 2024). "Notably, under hypoglycemia, taurine plasma levels were significantly lowered in the HAAF patients and in the Trpc5fx/0;DBH-Cre+ mice." (PMID 39375537, 2024). "In addition to TH, three episodes of insulin-induced hypoglycaemia also increased AADC and PNMT protein expression, while both recurrent glucoprivation and hypoglycaemia increased DBH protein expression within the adrenal gland." (PMID 38392992, 2024).
Insulin resistance (2 papers, 2017 to 2019). Increased resistance towards insulin, that is, diminished effectiveness of insulin in reducing blood glucose levels. "A preclinical study showed that DBH deficient mice exhibit hyperinsulinemia, lower plasma glucose levels, and insulin resistance." (PMID 29225702, 2017). "Also, patients having a rare homozygous mutation of DBH gene, showed impaired cardiovascular autonomic regulation, enhanced glucose-stimulated insulin secretion, and insulin resistance, the co-morbidities also observed in women with PCOS." (PMID 30946770, 2019).
neurogenic orthostatic hypotension (2 papers, 2023). "Whereas Droxidopa is a drug used to treat non-diabetic autonomic neuropathy, primary autonomic failure, and symptomatic neurogenic orthostatic hypotension (nOH) brought on by dopamine beta-hydroxylase deficiency." (PMID 38274093, 2023).
orthostatic hypotension (2 papers, 2023 to 2024). Sudden fall of the blood pressure of at least 20/10 mm Hg when a person stands up. "LOF mutations of DBH typically present with very low levels of NE and severe orthostatic hypotension and eyelid ptosis, but normal intellectual development and no record of ADHD symptoms." (PMID 39619336, 2024). "Humans with DBH deficiency also display orthostatic hypotension and in rare cases sudden cardiac death with CCS fibrosis." (PMID 38016975, 2023).
viral infection (2 papers, 2022). "Indeed, when DDC protein levels are downregulated under conditions not related to a viral infection, such as upon DDC silencing, a concomitant reduction of DBH expression occurs." (PMID 35336971, 2022).
brain injury (1 paper, 2026). Acute and chronic (see also brain INJURIES, CHRONIC) injuries to the brain, including the cerebral hemispheres, CEREBELLUM, and brain STEM. "Neurotransmission-related genes (BDNF, COMT, DRD1–3, DBH, SLC6A4, HTR2A, APOE) influenced motivation, fatigue, cognitive performance, and brain injury recovery." (PMID 41596414, 2026).
cerebral aneurysm (1 paper, 2024). "Conversely, elevation in apoC-I (OR: 0.1501, 95% CI: 0.0237-0.9526, PIVW: 0.0433), DBH (OR: 0.6810, 95% CI: 0.5136-0.9030, PIVW: 0.0076), and SP-D (OR: 0.7514, 95% CI: 0.5724-0.9864, PIVW: 0.0395) was associated with a decreased risk of cerebral aneurysm." (PMID 39253091, 2024).
Cirrhosis (1 paper, 2013). A chronic disorder of the liver in which liver tissue becomes scarred and is partially replaced by regenerative nodules and fibrotic tissue resulting in loss of liver function. "DBH expression was markedly upregulated in livers with NAFLD cirrhosis." (PMID 24019886, 2013). "DBH was expressed by near normal livers and markedly upregulated in livers with NASH cirrhosis compared to near normal controls (mean counts of DBH positive cells 17±1 vs. 2±2, n = 5, p<0.001)." (PMID 24019886, 2013).
diabetes (1 paper, 2017). "For many years now, scientists are connecting the DBH enzyme activity with diabetes and other high risk phenotypes, but the underlying mechanisms are not yet fully elucidated." (PMID 29225702, 2017).
dysautonomia (1 paper, 2024). An acute or chronic disorder, affecting the sympathetic or parasympathetic nervous system. "While there is no report of male infertility in ATP7A-related disease literature, retrograde ejaculation is a known symptom of dysautonomia associated with deficiency of dopamine-beta-hydroxylase (DBH), a copper dependent enzyme." (PMID 38141875, 2024).
Dystonia (1 paper, 2015). An abnormally increased muscular tone that causes fixed abnormal postures. "The early-onset torsion dystonia gene (DYT1), which encodes torsinA, an ATPase, has been found to be associated with dystonia and attention deficit disorder, as have neighboring DBH alleles." (PMID 25978647, 2015).
gastric cancer (1 paper, 2021). A primary or metastatic malignant neoplasm involving the stomach. "Subsequently, NE synthetase enzymes tyrosine hydroxylase (TH), dopa decarboxylase (DDC), and dopamine-β-hydroxylase (DBH), degrading enzymes monoamine oxidase A and B (MAOA and MAOB), and catechol-O-methyl transferase (COMT) were analyzed in TCGA database of gastric cancer." (PMID 33855088, 2021).
heroin dependence (1 paper, 2020). Physical and psychological dependence on the drug heroin. "In conclusion, our results supported the important role of DBH rs1611114 in memory change of heroin dependence." (PMID 32736537, 2020). "We found that DBH rs1611114 TT genotype had a protective effect on memory impairment after heroin dependence (P = 0.002, OR = 0.610)." (PMID 32736537, 2020). "This study aimed to identify the association between genetic polymorphisms of DA synthesis and metabolism genes, including tyrosine hydroxylase (TH), DOPA decarboxylase (DDC), solute carrier family 6 member 3 (SLC6A3) and DA beta-hydroxylase (DBH), with six important phenotypes of heroin dependence." (PMID 32736537, 2020).
intervertebral disc degeneration (1 paper, 2017). "Previous studies on intervertebral disc degeneration models have not addressed the expression of other sympathetic nervous system-related molecules, such as DBH, NPY, SOM, LENK, and GAL." (PMID 28762133, 2017).
malaria (1 paper, 2020). Malaria is a serious and sometimes fatal disease caused by a parasite that commonly infects a certain type of mosquito which feeds on humans. "However, further studies are required to determine if other 20E agonists, such as DBH, share similar mechanisms of limiting malaria parasites." (PMID 33273588, 2020).
melanoma (1 paper, 2020). A malignant, usually aggressive tumor composed of atypical, neoplastic melanocytes. "Both macrophages and melanoma cells expressed the norepinephrine synthesizing enzyme dopamine beta-hydroxylase (DBH)." (PMID 32353988, 2020).
Menkes disease (1 paper, 2015). A usually severe multisystemic disorder of copper metabolism, characterized by progressive neurodegeneration and marked connective tissue anomalies as well as typical sparse abnormal steely hair. "In the cells of patients with Menkes disease, the activity of DBH is significantly diminished and cannot be improved by parenteral Cu administration." (PMID 26732058, 2015).
mood disorder (1 paper, 2021). A cognitive disorder a disturbance in which the person's mood is hypothesized to be the main underlying feature. "However, few studies explored the association between DBH gene polymorphisms and mood disorders." (PMID 33995135, 2021).
neuroblastic tumor (1 paper, 2021). A group of nervous system tumors which display neuronal differentiation. "In turn, neuron-specific enolase (NSE), HISL19, and dopamine beta-hydroxylase have emerged as key markers for the diagnosis of neuroblastic tumors by IHC." (PMID 34638431, 2021).
osteoporosis (1 paper, 2025). A condition of reduced bone mass, with decreased cortical thickness and a decrease in the number and size of the trabeculae of cancellous bone (but normal chemical composition), resulting in increased fracture incidence. "It showed that in osteoporosis patients, CP (P < 0.01), LIPT1 (P < 0.05), SLC25A3 (P < 0.001), and UBE2D3 (P < 0.01) were upregulated, while the expression levels of CDKN2A (P < 0.05), DBH (P < 0.01), DLST (P < 0.05), LOXL2 (P < 0.05), SLC31A1 (P < 0.05), and UBE2D1 (P < 0.01) were downregulated." (PMID 40980812, 2025).
Paranoia (1 paper, 2008). The feeling and belief that one is being targeted or is a focus of negative or untoward actions, overt or covert, from others. "Additionally, the haplotype containing the two low DbH activity alleles was also associated with cocaine-induced paranoia." (PMID 18173840, 2008).
ptosis (1 paper, 2016). The drooping of the upper eyelid. "DBH deficiency prevents NE production and causes sympathetic failure, hypotension and ptosis in humans and mice; DBH knockout (Dbh -/-) mice reveal other NE deficiency phenotypes including embryonic lethality, delayed growth, and behavioral defects." (PMID 27148966, 2016).
sickle cell disease (1 paper, 2023). Sickle cell anemias are chronic hemolytic diseases that may induce three types of acute accidents: severe anemia, severe bacterial infections, and ischemic vasoocclusive accidents (VOA) caused by sickle-shaped red blood cells obstructing small blood vessels and capillaries. "In that regard, we investigated the potential role of DBH variants on the heterogeneity of acute and chronic pain phenotypes in sickle cell disease (SCD)." (PMID 37384335, 2023).
stereotypy (1 paper, 2012). "Alternatively, interaction of disulfiram with targets other than DBH may partially interfere with its ability to facilitate cocaine-induced stereotypy." (PMID 23209785, 2012). "Combined, all of these results suggest that disulfiram facilitates cocaine sensitization by inhibiting DBH; the ability of disulfiram to enhance cocaine-induced stereotypy is shared by a selective DBH inhibitor and abolished in the absence of DBH." (PMID 23209785, 2012).
tumor (16 papers, 1983 to 2026). "Both populations expressed classical adrenergic markers NPY and DBH in the core of the tumor, and this core was surrounded by macrophages, cancer-associated fibroblasts, and Schwann cell-lineage components in the periphery." (PMID 41279557, 2025). "In primary tumors, neuroblast clusters expressing adrenergic markers (e.g., NPY and DBH) dominated the tumor core and were bordered by stromal and immune components, with limited T cell infiltration." (PMID 41279557, 2025). "In contrast, induction of AP-2β expression has been found to impair tumour cell proliferation and slow tumour progression by enhancing both differentiation of noradrenergic neurons as well as noradrenergic signalling through increased expression of TH and DBH." (PMID 36076256, 2022). "Nervous system developmental genes, including NTRK1 and DBH were found to be highly expressed in the favourable tumour cluster h1." (PMID 21492432, 2011). "The expression of dopamine beta-hydroxylase suggests that tumor cells may have the ability to produce norepinephrine and may be another source of norepinephrine in the tumor environment." (PMID 32353988, 2020). "Indeed, in our NB murine model, immunofluorescence on tumor masses showed that NB tumor cells were positive for the Dopamine β-Hydroxylase (DBH), enzyme responsible for the norepinephrine synthesis, regardless of the β3-AR expression on tumor or its antagonism." (PMID 36854895, 2023). "Our analysis supports this link between the expression of key noradrenergic‐related genes, such as DBH, SLC6A2, and their downstream ADRA/ADRB receptors, with increased tumor severity in TCGA‐LIHC samples." (PMID 41347690, 2025). "Specifically, genes such as TRIM71, DBH, HP, FER1L4, and GCH1 exhibited dynamic and progressive expression changes along tumor grades, with significant increases in Grade 4 tumors compared to Grade 1 (Wilcoxon test, adj." (PMID 41347690, 2025). "Some patients with HN-PG/non-chromaffin cell tumours and sympathetic PCPG had elevated plasma 3-methoxytyramine (3-MT) (a dopamine metabolite) and these tumours had low DBH expression - DBH being necessary to convert dopamine to norepinephrine." (PMID 38978571, 2024). "However and in contrast to peripheral DBH deficiency, IL-4ra deficiency did not reduce HSL phosphorylation or adipose tissue atrophy of tumor-bearing mice, despite reduced β-adrenergic signaling." (PMID 35210363, 2022).
psychiatric disorder (4 papers, 2013 to 2021). A disorder characterized by behavioral and/or psychological abnormalities, often accompanied by physical symptoms. "Low levels of DBH in the plasma or cerebrospinal fluid (CSF) are associated with greater susceptibility to positive psychotic symptoms in several psychiatric disorders (17(." (PMID 28050184, 2016). "Several genetic variations and SNPs in DBH are associated with psychiatric disorders such as ADHD." (PMID 34492034, 2021).
cancer (3 papers, 2024 to 2025). A tumor composed of atypical neoplastic, often pleomorphic cells that invade other tissues. "We applied this in our GEMM tumors, a model that develops neuroblastoma because of Cre-conditional activation of the human copy of MYCN in dopamine beta-hydroxylase (Dbh) expressing cells—thus, human MYCN expression should be excluded from non-cancer cells." (PMID 38898465, 2024).
infection (3 papers, 2016 to 2023). The state of being infected such as from the introduction of a foreign agent such as serum, vaccine, antigenic substance or organism. "Higher mRNA levels of MAOA, MAOB and VMAT2 were observed upon infection in these cells also, while DBH and COMT expression was not significantly altered." (PMID 36611805, 2022).
metabolic disorder (2 papers, 2017 to 2025). "DBH deficiency is an extremely rare metabolic disorder of catecholamine synthesis, described in less than 20 patients worldwide." (PMID 27858196, 2017).
neurological diseases (2 papers, 2007 to 2009). "In this study, we measured the level of DBH activity in the serum of patients of three different age groups (8–14 yrs, 20–40 yrs and 45–60 yrs) suffering from neurological diseases." (PMID 23675164, 2009). "Since DBH activity decreases in neurological disorders, it may be useful as one of the parameters to diagnose such disorders." (PMID 23675164, 2009). "The COMT and DBH genes are physically located at chromosomes 22q11 and 9q34, respectively, and both COMT and DBH are involved in catecholamine metabolism and are strong candidates for certain psychiatric and neurological disorders." (PMID 18466599, 2007).
DBH also shares sentences with these, for which no sentence is quoted: bipolar disorder (3 papers); epilepsy (2); Hepatitis (2); post-traumatic stress disorder (2); psychosis (2); age (1); alcohol use disorders (1); autoimmune disease (1); Blindness (1); cardiovascular disease (1); cataract (1); cervical dystonia (1); cocaine use disorder (1); congestive heart failure (1); diabetic autonomic neuropathy (1); dizziness (1); Dyskinesia (1); dysphoria (1); Encephalopathy (1); heart failure (1); Hyperinsulinemia (1); inflammatory bowel disease (1); male infertility (1); memory impairment (1); men (1); mental disorder (1); migraine with aura (1); multiple system atrophy (1); nicotine addiction (1); obsessive-compulsive disorder (1).
A further 7 diseases each share a sentence with DBH in 1 paper.